MKI67P1 (marker of proliferation Ki-67 pseudogene 1)
Gene: Processed pseudogene on chromosome X (46,560,928 to 46,562,749, reverse strand). Ensembl gene ENSG00000270499.
Diseases named in the same sentence as MKI67P1 in open-access papers:
MKI67P1 is named in the same sentence as 2 diseases in open-access papers, as found by Europe PMC text mining. Sharing a sentence is not in itself a finding about the gene and the disease. The quoted sentences say what the papers report.
prostate carcinoma (1 paper, 2020). A carcinoma that arises from epithelial cells of the prostate gland. "We used univariate and multivariate Cox regression analysis to identify seven prognostic signatures for prostate cancer patients, including BCO1, BAIAP2L2, C7, AP000844.2, ASB9, MKI67P1, TMEM272." (PMID 32547947, 2020).
cancer (1 paper, 2020). A tumor composed of atypical neoplastic, often pleomorphic cells that invade other tissues. "AP000844.2, MKI67P1, and TMEM272 were rarely reported in current studies related to cancer, but were classified as risk prognostic genes in this study." (PMID 32547947, 2020).